CD4 (CD4 molecule)
Diseases named in the same sentence as CD4 in open-access papers (continued):
Sharing a sentence is not in itself a finding about the gene and the disease.
Hepatitis (continued). "Th17 cells, another subset of CD4+ T cells, secrete IL-17, associated with liver inflammation and fibrosis.Although Treg and Th17 cells are both differentiated from CD4+ T cells, they are mutually transformed during their differentiation and have mutually restricting functions." (PMID 37875903, 2023). "We therefore performed a detailed analysis of CD8 and CD4 T cell subsets in the discovery cohort and analyzed potential associations of these immune populations with age and the incidence of hepatitis." (PMID 36503532, 2022). "Moreover, CD4 count is purportedly associated with decreased humoral response to multiple vaccines, including hepatitis A, hepatitis B, and pneumococcus vaccines among PWLH." (PMID 35791004, 2022). "Similar results were obtained in a very recent report, where it was demonstrated that a subset of patients predisposed to ICI-related hepatitis may be identified by expanded CD4+ effector memory T cells." (PMID 34360781, 2021). "Therefore, our biochemical and radiological investigations argue against pre-treatment liver inflammation as a common cause for baseline CD4+ TEM expansion and treatment-related hepatitis." (PMID 33664251, 2021). "Experimental studies in animals have demonstrated that liver injury in ConA-induced hepatitis is associated with activated CD4+T cells, macrophages, and natural killer T (NKT) cells that cause hepatocyte injury by producing lots of pro-inflammatory cytokines, particularly IFN-γ and TNF-α." (PMID 32742600, 2020). "The relative deficiency in effector CD4+ T cells in the lead up to overt hepatitis may also have contributed to pathogenesis." (PMID 29289977, 2018). "Although some studies have shown that a CD4+ T-cell count nadir below 100–200 cells/μL and hepatitis C virus co-infection are factors associated with FV, but our findings do not support these observations nor a relationship with the previous time on virological suppression." (PMID 26872331, 2016). "Loss of CD4 T cell help correlates with virus persistence during acute hepatitis C virus (HCV) infection, but the underlying mechanism(s) remain unknown." (PMID 23818845, 2013). "Usage of NRTIs might slightly worsen liver function with very low frequency and NVP might be associated with hepatitis on the background of high baseline CD4+ T cell counts." (PMID 21858166, 2011). "Indeed the association between hepatitis viral co-infection and CD4+ T lymphocytes count is currently a subject of debate, with some studies showing no existence of a relationship and others showing the association." (PMID 19099553, 2008). "CD4 cell counts are more predictive of hepatotoxicity among men than women (i.e., men who have a CD4 cell counts > 400 cells/mm3 are at a greater risk of hepatitis than women with CD4 cell counts > 250 cells/mm3)." (PMID 16120209, 2005). "Although the initial injury may be distinct, similar cellular and molecular dysfunctions causing unregulated CD4+ T cell–mediated inflammation, progressive fibrosis, and ultimately organ failure are seen in diseases such as heart failure, hepatitis, renal, and pulmonary fibrosis." (PMID 37159282, 2023). "Here, circulating CD4+ T cells with high programmed cell death 1 (PD-1) and ICOS coexpression were temporally associated with onset of virus control, seroconversion, and hepatitis in HCV-infected chimpanzees." (PMID 40956619, 2025). "Positive cases were referred to midwives, with HIV-positive women receiving further tests like viral load, CD4 counts and hepatitis screenings." (PMID 40459110, 2025). "Regarding CD4+ cytotoxic T cells (CTLs), these are predominantly associated with late differentiated T cell states found in persistent infections like CMV, Hepatitis or HIV86–90." (PMID 41350288, 2025). "In models of sterile tissue injury, such as cisplatin-induced kidney damage and concanavalin A-induced hepatitis, CD4+ T cells producing IFN-γ and IL-17, as well as CD8+ T cells producing IFN-γ, have been shown to contribute to tissue damage." (PMID 41294914, 2025).
Hepatitis (continued). "PD-1hiICOShi CD4+ Tfh1-like cells also peaked after hepatitis A virus infection, but the response was accelerated by several weeks compared with HCV infection." (PMID 40956619, 2025). "Risk factors such as low CD4 count in HIV-infected individuals, pre-existing hepatitis, and hypo-albuminemia also contributed to post-TB liver injury." (PMID 39502524, 2024). "Accordingly, using the unrestricted dataset, CD27+ CD28+ CD4+ TEM (%) correctly predicted the incidence of hepatitis in 74 of 110 patients." (PMID 38926389, 2024). "Similar observations of an impaired effector memory CD4 T-cell response were made in patients on dialysis two weeks after hepatitis B vaccination." (PMID 39265505, 2024). "The total predicted immune cell count was greater in the NASH cluster than the Normal/NAFLD, with an increase in CD8 and CD4 T cells and dendritic cells, and a decrease in M2 macrophages and mast cells confirming the hepatitis that is characteristic of NASH." (PMID 38291075, 2024). "Hepatitis caused by this strain seems to be T-cell-mediated given that higher frequencies of IFNγ-producing CD8 T cells were associated with more severe disease and depletion of either CD8 or CD4 T cells reduced the severity of MCMV-induced hepatitis." (PMID 39134803, 2024). "Here 25–34% of diagnoses occurred when participants had CD4 counts of > = 500 cells/μl blood around their hepatitis diagnosis and 42–55% CD4 counts of < 350 cells/μl." (PMID 39476279, 2024). "Hepatic histopathological analysis, serum transaminase concentrations, and the proportion of CD4+ T cell subsets in the liver and spleen were performed to assess the progression degree of hepatitis." (PMID 37775797, 2023). "Collectively, these data suggest that CD73 plays a significant role in the immunoregulatory capacity of ERCs in downregulating the population of splenic CD4+ T cells in Con A-induced hepatitis." (PMID 37775797, 2023). "It has also been proposed that IL-37 can reduce Con-A-induced hepatitis by inhibiting the activity of DCs, blocking the biological effect of CD4+ T cells, increasing the proportion of Tregs and enhancing their function." (PMID 37215069, 2023). "The standard clinical T- and B-cell flow cytometry panel did not identify significant differences between groups, however there was a trend toward more activated T-cells (HLA-DR+) and a decreased CD4:CD8 T-cell ratio in the activated T-cell hepatitis patients." (PMID 37267251, 2023). "We and others previously have demonstrated ERC’s valuable effectiveness in treating autoimmune and inflammatory diseases, including experimental hepatitis by the inhibition of CD4+ conventional T cells." (PMID 37775797, 2023). "In postpartum hepatitis mother, CD4+ T cells secreted more IFN-γ, IL-21, IL-2, TNF-α, and secreted more pro-inflammatory/anti-inflammatory cytokines." (PMID 36685527, 2022). "Meanwhile, naïve CD4 + T cells showed a lower outgoing interaction strength in health, hepatitis, and cancer states, but their outgoing strength increased in the cirrhosis state." (PMID 36221095, 2022). "Compared with the group without postpartum hepatitis, the number of Treg in delivery woman with postpartum hepatitis was low, the ratio of CD4+ T cells expressing activated marker CD69 was significantly higher." (PMID 36685527, 2022). "In our trajectory analyses of four states, the phenomenon that naïve CD4 + T cell differentiated into Treg occurred first in cirrhosis and then became more obvious in cancer, which was unobserved in health and hepatitis." (PMID 36221095, 2022). "These included other HIV-related measurements such as CD4 count and additional blood tests (e.g., hepatitis and sexually transmitted infections (STIs))." (PMID 35207719, 2022). "Pre-therapy CD4+ TEM expansion predicts hepatitis in CMV-seropositive patients, opening possibilities for avoidance or prevention." (PMID 33664251, 2021).
Hepatitis (continued). "This study identifies pre-therapy expansion of CD4+ effector memory T cells (TEM) in CMV-infected patients with metastatic melanoma as a prognostic marker of αPD-1/αCTLA-4-related hepatitis." (PMID 33664251, 2021). "Whereas 12 of 12 CD4+ TEM≥21% patients treated with αPD-1/αCTLA-4 dual therapy developed hepatitis, 3 of 4 CD4+ TEM≥21% patients who received αPD-1 monotherapy remained hepatitis free." (PMID 33664251, 2021). "This retrospective comparison showed 18F-FDG standard uptake ratios (SURmean liver) were higher in CD4+ TEM<21% patients than CD4+ TEM≥21% patients with hepatitis." (PMID 33664251, 2021). "In our study, valganciclovir prophylaxis apparently prevented hepatitis in four of four CMV IgG+ CD4+ TEM≥16% patients." (PMID 33664251, 2021). "This surprising discovery stemmed from our observation that pre-treatment expansion of CD4+ effector memory T cells (TEM) in the blood reliably predicts hepatitis." (PMID 34868015, 2021). "Our previous work established a cut-off ≥16% CD4+ TEM cells as a predictor of checkpoint blockade-related hepatitis in CMV Ig+ patients." (PMID 34868015, 2021). "Hepatitis in CD4+TEMlow patients tends to occur in younger individuals with lower numbers of circulating CD14+ monocytes." (PMID 34868015, 2021). "We plan to conduct a randomised, prospective, multicenter clinical trial to test the efficacy of valganciclovir prophylaxis in preventing hepatitis in CD4+ TEMhigh patients." (PMID 34868015, 2021). "Collectively, these mouse and human studies suggest a role for CD4+ memory T cell subsets in diet-induced liver inflammation and steatosis-to-fibrosis progression." (PMID 33013934, 2020). "Although CD4+ T cells play important roles in both ConA-induced hepatitis and EAU, apparently treatment with DH suppressed the production of inflammatory cytokines by CD4+ T cells through different mechanisms in these two disease models." (PMID 33117376, 2020). "Hepatocytes, which do not normally express MHC class II molecules, acquire the ability to express MHC II and activate CD4+ T cells during hepatitis." (PMID 31787967, 2019). "Garrido in his study on 125 patients with viral hepatitis and 125 matched patients as a control group reported a negative correlation between sperm progression and serum level of CD4+ and positive correlation between sperm motility and hepatitis improvement." (PMID 31583372, 2019). "Con A-induced hepatitis is similar to human AIH in that the liver aggregates mainly CD4 + T cells, which mediates liver injury." (PMID 30893870, 2019). "Mass cytometry revealed a number of CD4+ T cell abnormalities that were stably present in the hepatitis patient several months before the onset of disease." (PMID 29289977, 2018). "CD4+ T cells have been shown to play a fundamental role in conducting liver inflammation in Con A-induced hepatitis." (PMID 29643811, 2018). "Treatment with an anti-CD4 antibody attenuated, but only partly, ConA-mediated hepatitis, indicating that activated CD4+ T cells are responsible for the disease progression." (PMID 30462657, 2018). "To further clarify the role of T cells (CD4+ cells) in ConA hepatitis, we treated WT and Ramp1-/- mice with an anti-CD4 antibody 24 h before ConA treatment." (PMID 30462657, 2018). "Here we review the pathogenesis of hepatitis induction by anti-PD-1 and the possible role of resistance of CD4+ T cells to corticosteroids in treatment of this patient." (PMID 29289977, 2018). "In the hepatitis patient, the number of CD4+ T cells was reduced more than twofold in response to steroid therapy, while CD8+ T cells dropped by a third, and the absolute numbers of circulating NK cells and B cells increased." (PMID 29289977, 2018). "In contrast, ATG reversed the deficit in effector CD4+ T cells present in all the patient’s pre-hepatitis samples." (PMID 29289977, 2018). "ULBP1 was also selectively elevated on CD4 T cells from patients with HBV-related liver inflammation (serum ALT >60 IU/l)." (PMID 28031333, 2017).
Hepatitis (continued). "CD8+ and CD4+ clones from liver biopsies of patients with acute hepatitis A were strongly cytotoxic, and released IFN-γ, which was correlated with the anti-viral response." (PMID 28703774, 2017). "In earlier reports, CCR10-expressing CD25+CD4+FOXP3+ Treg cells were identified to be critical for maintaining the potent anti-inflammatory properties in liver inflammation." (PMID 27716621, 2016). "Immune cells involved in ConA-induced hepatitis include CD4+ T cells, natural killer T cells, Tregs, Kupffer cells, neutrophils, and eosinophils." (PMID 24981055, 2014). "Constructing ConA-induced hepatitis model on Treg-depleted mice, we found that depletion of Tregs upregulated CD4+CD69+ T cells in the liver and spleen." (PMID 24981055, 2014). "To study the role of CD4+ T cells in LCMV-induced hepatitis, we compared the outcome of LCMV infection in wild-type C57BL/6 mice that have normal CD4+ T-cell numbers with that in CD4+ T cell-lymphopenic C57BL/6 mice." (PMID 24466045, 2014). "Th17 cells are a newly discovered subset of CD4 + T cells, which are related to liver inflammation and fibrosis." (PMID 24403916, 2013). "We conclude here that DMY protects animals against fuminant hepatitis induced by LPS/D-GalN at least in part by attenuating inflammatory cell and CD4+ T cell activities." (PMID 24143247, 2013). "Our experiments revealed that the induction of hepatitis by CD4+ T cells depended at least in part on TNFα." (PMID 21966366, 2011). "CD4+ and NK cells levels in Group A were lower after progression into severe hepatitis than on the second day of admission (baseline) (P < 0.01)." (PMID 22224079, 2011). "Co-transfer of effector OT-II T-cells with low numbers of OT-I T-cells lead to ALT-release, thus converting a sub-threshold damage elicited by CD8 T-cells alone to overt hepatitis when CD4 T-cell help is provided." (PMID 21779338, 2011). "Significantly increased numbers of CFSE+ cells were observed in liver and spleen of mice suffering from hepatitis as compared to controls, demonstrating enhanced recruitment of CD4 T-cells to these organs." (PMID 21779338, 2011). "If this patient is co-infected with hepatitis and on cART for more than 24 months, the CD4 count slope is below 20 cells/μL even the concurrent HIV VL is 500 copies/mL." (PMID 21182796, 2010). "If this patient was hepatitis co-infected, the CD4 count starts to fall when the HIV VL increases up to 3 000 copies/mL." (PMID 21182796, 2010). "The evaluation included clinical assessment and determination of CD4+ T-lymphocyte count, serum transaminases and serology for Hepatitis A, B and C markers by ELISA." (PMID 19099553, 2008). "A 31-year old male in group B who developed clinical hepatitis had a baseline CD4 cell count of 17 cells/mm3 and plasma NVP level of 10.2 mg/l." (PMID 17352798, 2007). "In contrast, in an α-GalCer–induced hepatitis mouse model, pharmacological Galectin-3 neutralization could increase the percentage of CD4+CD25+FOXP3+ Treg cells and TGF-β–producing Treg cells among liver-infiltrating cells." (PMID 41477833, 2026). "It has been demonstrated that CD4 + T cells do not cause hepatitis in the absence of CD8 + T cells and are less prone to activation by liver antigens under non-inflammatory conditions." (PMID 41343465, 2025). "The discriminatory cutoff for patient classification, defined by the Youden index, was the same for both the restricted and unrestricted datasets, such that samples with more than 9.56% of CD27+ CD28+ CD4+ TEM relative to CD4+ are predicted to be hepatitis positive." (PMID 38926389, 2024). "In the present study, we found that ERCs could significantly inhibit the enhancing immunity function of CD4+ T cells both in vitro and in Con A-induced hepatitis response, while there was an apparent recovery when CD73 was knocked out on ERCs." (PMID 37775797, 2023). "The transfer of CD4+ T cells extracted from mice with AIH could induce liver inflammation in recipient mice." (PMID 38137182, 2023).
Hepatitis (continued). "The most discriminatory marker for hepatitis was CD4+ T cell frequency (AUC=0.630)." (PMID 36248910, 2022). "In sum, in this work, we could not confirm a clinically relevant role of virus serology or TEM CD4 T cell populations in patients who later developed hepatitis as previously reported." (PMID 36503532, 2022). "We speculated that naïve CD4 + T cells may be regulated by macrophages through paracrine mechanisms, mainly in hepatitis, cirrhosis, and cancer." (PMID 36221095, 2022). "Over-activated CXCR5+CD4+ T cells could help B cells to secret autoantibodies and accelerate liver inflammation." (PMID 35223685, 2022). "Applying this stringent cut-off to our validation cohort of patients with unresectable metastatic disease allowed us to correctly predict hepatitis in 6 of 6 patients with CD4+ TEM≥21% (specificity = 100%) and correctly identify 6 of 20 patients who developed hepatitis (sensitivity = 30.0%)." (PMID 33664251, 2021). "When considering only CMV IgG+ cases, CD4+ TEM % was a more discriminatory marker of hepatitis." (PMID 33664251, 2021). "We propose CMV-driven T cell responses are a single, but salient example of a general mechanism responsible for hepatitis after checkpoint blockade because other viruses or toxic agents could also drive chronic CD4+ T cell activation before therapy." (PMID 33664251, 2021). "Comparing the frequency of 50 principal leucocyte subsets between patients who subsequently did (n = 18) or did not (n = 26) develop hepatitis revealed significant over-representation of CD4+ TEM cells associated with hepatitis." (PMID 33664251, 2021). "CD4+ T cells were reported to play a critical role in ConA-induced hepatitis in wild-type mice." (PMID 34654474, 2021). "Hence, baseline CD4+ TEM expansion is a specific, but relatively insensitive prognostic marker of individuals who are predisposed to hepatitis after αPD-1/αCTLA-4 therapy." (PMID 33664251, 2021). "Reducing the incidence hepatitis by opting for αPD-1 monotherapy hints that CTLA-4 blockade may be mechanistically important for development of hepatitis in CD4+ TEM≥21% patients." (PMID 33664251, 2021). "Consistent with the notion that hepatitis results from cell-intrinsic responses, prior depletion of CD4+ or CD8+ T cells, NK/NK-T cells, or phagocytic macrophages has no impact on the development of hepatitis following intravenous challenge of Ifnar1-/- mice with HAV." (PMID 34591933, 2021). "The CD4/CD8 ratio correlates with chronic inflammation and immune senescence, even in virologically suppressed and immunologically controlled PLHIV and has been associated with poor hepatitis A and hepatitis B vaccine responses." (PMID 34987514, 2021). "LSECs have been described to prime tolerance through CD8+ T presentation in low antigenic concentration and even to activate CD4+ T cells to become regulatory and, therefore, protective while suppressing inflammatory CD4+ T cells in a model of T cell-mediated hepatitis." (PMID 32429209, 2020). "Furthermore, they immunohistochemically revealed the presence of numerous CD3+ and CD8+ lymphocytes, whereas ICI‐associated hepatitis contained fewer CD20+ plasma cells and CD4+ T cells than AIH." (PMID 32068351, 2020). "Thus, enclysis is a biological process with potential effects on immunomodulation and opens a new field for research to fully understand CD4+ T cell dynamics in liver inflammation." (PMID 31693899, 2019). "In addition, more CD4+ T cells than macrophages expressed these cytokines, suggesting that CD4+ T cells are the main source of TNFα and IFNγ during ConA hepatitis." (PMID 30462657, 2018). "In addition to CD4+ T cells, neutrophils, natural killer T cells and Kupffer cells essentially contribute to the inflammatory process in Con A-induced hepatitis." (PMID 29643811, 2018). "In this context, agents that can suppress CD4+ T-cells infiltration could possess protective activity against Con A-induce hepatitis." (PMID 29643811, 2018).